CRP (C-reactive protein)
Diseases named in the same sentence as CRP in open-access papers (continued):
Sharing a sentence is not in itself a finding about the gene and the disease.
Stroke (continued). "We next evaluated whether alterations in laboratory parameters including hemoglobin, WBC, platelets, LDH, CRP, d-dimers, and fibrinogen were associated with cancer diagnosed after stroke." (PMID 36596831, 2023). "Similarly, a recent study showed that higher CRP levels in the early post-stroke phase up to 72 h, were associated with increased risk of stroke recurrence at 1 year." (PMID 37119383, 2023). "Elevated CRP levels are closely associated with both acute and chronic inflammatory conditions, spanning across a broad spectrum of disorders including infection, trauma, stroke, tissular necrosis, and neoplasms." (PMID 37760885, 2023). "Similarly, in a cohort of 425 patients with AF-related cardioembolic stroke (CES) from the Fukuoka Stroke Registry, CRP was independently associated with recurrent stroke at one year (HR 1.02, 95% CI 1.00–1.02, per 1mg/L increase)." (PMID 41541100, 2023). "These hypothesis-generating data suggest that IL-6 may have clinical utility as a more specific inflammatory risk marker for predicting recurrent stroke and vascular events compared with CRP." (PMID 41541100, 2023). "On the other hand, we cannot exclude the possibility that this CRP elevation was associated directly to stroke and the release of IL-1β both in the brain and in the systemic circulation, inducing a cascade of sympathetic system activation catecholamine release in the extracellular myocardium." (PMID 37119383, 2023). "Higher levels of CRP were associated with cancer diagnosed within 1 and 3 years after stroke (p = 0.02 and p = 0.042) as well as higher d-dimers were associated with cancer diagnosed within 3 years after stroke (p = 0.019)." (PMID 36596831, 2023). "In the stratified analysis by age group, increased hs-CRP was significantly associated with an increased hazard of stroke and CVD among subjects aged < 60 years [HR (95% CI): 2.18 (1.37–3.45) and 1.67 (1.16–2.39); all P < 0.05], not among subjects aged ≥ 60 years (P > 0.05)." (PMID 37403063, 2023). "CRP retained its independent association (HR 1.47 (1.15–1.87)) with death in the stroke population." (PMID 35042473, 2022). "Higher D‐dimer and CRP levels are associated with cancer, especially lung cancer, and previous studies have also shown that patients with lung cancer have a higher risk of stroke." (PMID 36065806, 2022). "Moreover, some clinical and biochemical indexes, such as hemoglobin or high-sensitivity C-Reactive Protein (hs-CRP) have been reported to be significantly associated with the incident stroke risk." (PMID 35953770, 2022). "In addition, CRP has been shown to be an independent predictor of the risk of myocardial infarction, stroke and peripheral vascular disease and can be used to predict future risk in patients with stable and unstable angina." (PMID 36418968, 2022). "CRP levels correlate with IS severity and can be a marker of IS etiology, with higher CRP in more severe cardioembolic or large artery disease stroke than in stroke caused by small artery disease." (PMID 36448063, 2022). "As expected, established risk factors (myeloid CH, age, sex, ethnicity, smoking status, cholesterol, HbA1C, HDL, LDL, blood pressure, BMI, uACR, hs-CRP and eGFR scores) were associated on univariate analysis with an adverse outcome as defined by a composite endpoint of death, MI, or stroke." (PMID 34413458, 2022). "Moreover, a recent study has demonstrated an inverse association with IL-6 and high sensitivity C-reactive protein levels, suggesting a potential anti-inflammatory role for vitamin D in stroke individuals." (PMID 35681147, 2022). "Besides, a latest meta-analysis underscored that a higher level of CRP in the acute phase of stroke predicted an augmented risk of PSD." (PMID 36225923, 2022). "High CRP and IL-6 concentrations are risk factors for stroke." (PMID 36353279, 2022). "Furthermore, higher serum CRP levels have been found to be associated with post-stroke cognitive impairment (PSCI)." (PMID 34884906, 2021).
Stroke (continued). "Polymorphisms in IL-38 were associated with CRP concentrations in the sera of patients with stroke." (PMID 34830435, 2021). "Inflammatory risk markers including neutrophil, lymphocyte, and CRP may have strong independent prediction values for stroke outcome." (PMID 33314753, 2021). "Furthermore, elevated CRP levels independently predict the risk of future stroke and transient ischemic attack in the elderly." (PMID 34305782, 2021). "However, the main finding of the current qualitative study is that statin therapy in stroke patients is associated with reducing CRP as an acute-phase reactant and sensitive marker of systemic inflammation." (PMID 34489618, 2021). "A high CRP level is associated with an increased risk of developing stroke; nevertheless, whether the CRP level at the time of ED presentation is useful for stroke detection remains unknown." (PMID 34135849, 2021). "In addition, higher FPG (95% CI: 1.01–1.19, P = 0.029) and hs-CRP (95% CI: 1.00–1.02, P = 0.002) levels were also risk factors of mortality at 12 months after stroke onset." (PMID 33967939, 2021). "CRP is an inflammatory marker and positively associates with stroke." (PMID 33686964, 2021). "We found that inflammatory risk markers including neutrophil, lymphocyte, and CRP may have strong independent prediction values for stroke outcome." (PMID 33314753, 2021). "The CAMI-1 study introduces a new clinical tool: CRP apheresis may prove its usefulness in the treatment of inflammatory diseases such as other subtypes of acute coronary syndromes and stroke, in which CRP might be causally involved." (PMID 33778017, 2021). "A high serum CRP level has been associated with the risk of developing a stroke." (PMID 34135849, 2021). "In addition, CRP level had the greatest increase in patients with LAA stroke, and baseline CRP level can independently predict the risk of stroke recurrence." (PMID 33967939, 2021). "Apart from the risk of stroke, high CRP values are predictive of cognitive impairment." (PMID 34445740, 2021). "The observed changes in CRP align with the results of previous exercise interventions and highlight the value of including this biomarker of cardiovascular risk in future definitive trials among stroke survivors." (PMID 34070731, 2021). "CRP has been reported to be an independent risk factor in clinical stroke." (PMID 34856939, 2021). "CRP levels are increased in stroke and are associated with stroke incidence and outcomes." (PMID 33753837, 2021). "From the standpoint of neuroinflammation, inflammatory markers would be expected to be associated with stroke, suggesting that CRP could be used as a prognostic marker in acute stroke." (PMID 34135849, 2021). "Nevertheless, it was found that stroke-associated pneumonia was significantly associated with higher age, dysphagia, greater stroke severity, embolectomy treatment, insertion of nasogastric tubes, and higher CRP levels at BL." (PMID 33240188, 2020). "However, ADMA levels were associated with levels of IL-6 and CRP at several time points after stroke." (PMID 32150996, 2020). "Recently, it was reported that elevated serum levels of CRP could be a predictor for post-stroke disability and prognosis as well as a diagnostic marker for stroke-associated pneumonia." (PMID 33240188, 2020). "Sudden cardiac death may be the leading cause of post-stroke mortality because of the stronger association between CRP and cardiac injury." (PMID 30718369, 2019). "The association of CRP level with stroke outcome is currently unclear." (PMID 31653901, 2019). "Baseline levels of CRP are predictive of risk of myocardial infarction, and stroke." (PMID 29975702, 2018). "Notably, IL-6 has been reported to function as a main stimulator of CRP that predicts clinical stroke risk." (PMID 29403373, 2017). "Since CRP is a commonly measured biomarker, we believe that it could be a valuable contributor to a future multi-marker panel for determining the risk of stroke in HH patients." (PMID 29245986, 2017).
Stroke (continued). "Our results suggest that a CRP >25 mg/L should prompt investigations for pneumonia while values >65 mg/L have the highest diagnostic accuracy to justify consideration of this threshold as a diagnostic marker of post-stroke pneumonia." (PMID 26937636, 2016). "To determine whether CRP in the blood is independently associated with short-term outcomes after stroke, we prospectively enrolled patients with first-ever acute ischemic stroke within 24 h of onset and measured plasma CRP on admission using a uniform method." (PMID 27258004, 2016). "The association between CRP in the blood and post-stroke clinical outcomes is still unclear." (PMID 27258004, 2016). "Our results suggest that a CRP value >25 mg/L should prompt investigations for pneumonia while values above 65 mg/L have the highest diagnostic accuracy to justify consideration of this threshold as a diagnostic marker of post-stroke pneumonia." (PMID 26937636, 2016). "CRP is an acute-phase reactant that has been shown in many cohort studies to be a reliable measure of underlying systemic inflammation and a predictor of future myocardial infarction and stroke." (PMID 25816055, 2015). "We hypothesized that levels of lipopolysaccharide binding protein (LBP), interleukin-10 (IL-10), IL-6 and C-reactive protein (CRP) are early predictors for the development of stroke-associated infection." (PMID 25613713, 2015). "Thus a possible explanation for the changed association between CRP and fatigue over time is that the development of fatigue at different stages after stroke is affected or even dominated by different factors." (PMID 26599129, 2015). "Previous studies have suggested that C-reactive protein (CRP) was associated with risk of stroke." (PMID 25191699, 2014). "Finally, the RE-LY biomarker study showed an independent association between IL-6 and stroke or systemic embolism, while CRP levels were associated with cardiovascular mortality after multivariate adjustments." (PMID 25215263, 2014). "Acute infections have been reported to increase plasma fibrinogen and CRP levels, which may affect the risk of stroke." (PMID 24586739, 2014). "There was also a study showed high CRP level was a strong risk factor for fatal stroke." (PMID 25191699, 2014). "The concept of a pre-existing inflammatory condition is supported by evidence that low-grade inflammation, identified by an elevated CRP concentration, may be a risk factor for stroke." (PMID 24597828, 2014). "Previous literatures reveled CRP could increase the risk of stroke and post stroke vascular disease recurrence." (PMID 23317415, 2013). "Increased CRP was shown to be associated with poor prognosis when measured within 24 h of acute ischemic stroke, and elevated Hcy levels also have been found in stroke in previous studies." (PMID 24039853, 2013). "Risk factors for stroke (the CHADS2 and CHA2DS2-VASc score) and systemic (D-dimer and C-reactive protein) and local (left ventricular ejection fractions) factors may be associated with stroke phenotype." (PMID 21861923, 2011). "Speculatively, CRP may indirectly lead to cognitive impairment via promoting vascular disease i.e. causing stroke and transient ischemic attacks (TIAs), although recent genetic studies go against CRP as a causal agent in vascular disease." (PMID 21915265, 2011). "Previous stroke studies have shown an association between high CRP and poor outcome." (PMID 19400931, 2009). "Whether high CRP causes more severe stroke or vice versa needs to be further studied in population-based larger cohort studies, or in clinical studies with very early and closely spaced repeated measurements." (PMID 19400931, 2009). "The aim of this study was to help clarify the role of early CRP in ischemic stroke by determining its association with stroke severity, stroke etiology, functional outcome, mortality and future vascular events, in a larger study than most of the previous studies." (PMID 19400931, 2009).
Stroke (continued). "The association between high CRP and a high stroke severity remains unexplained." (PMID 19400931, 2009). "An elevated CRP was associated with increased stroke severity (NIHSS, OCSP) (p = 0.01, p = 0.006)." (PMID 19400931, 2009). "Therefore, not accounting for this variable may have introduced confounding effects affecting the associations observed between HDL cholesterol, CRP, and disability severity as stroke outcome." (PMID 41300462, 2025). "Additionally, studies had to report at least one of the following outcomes: incidence of MACE (e.g., myocardial infarction, stroke, or cardiovascular death), levels of inflammatory biomarkers (hs-CRP or IL-6), or adverse events associated with the intervention." (PMID 40688868, 2025). "Moreover, in the analysis of risk factors for cognitive impairment in stroke patients, CRP may be an important independent predictor of PSCI." (PMID 40852521, 2025). "Many inflammatory indicators (amyloid A, CRP, matrix metalloproteinases, myeloperoxidase, phospholipase A2, and others) and some OS indicators (malondialdehyde, protein carbonyls, and NO metabolites) have been identified as risk markers for stroke severity and prognosis." (PMID 41153334, 2025). "However, large population-based studies demonstrated that elevated FVIII levels were independently associated with an increased risk of coronary heart disease, and to a lesser extent, stroke, even after adjustment for traditional cardiovascular risk factors and CRP." (PMID 41007843, 2025). "Thus, METS-IR levels may indirectly affect the risk of stroke occurrence by influencing CRP levels, and this effect may extend to changes in cognitive function after stroke." (PMID 39634177, 2024). "Similarly, the risk of stroke was 1.3 times higher in individuals with CRP levels above 3 mg/L." (PMID 37760885, 2023). "Keywords such as “pathophysiology,” “c-reactive protein,” and “d-dimer” indicate that researchers have also been interested in understanding the biomarkers and potential diagnostic tools that may be used to identify patients at risk for stroke during COVID-19." (PMID 37077570, 2023). "Cancer-related strokes are often caused by paraneoplastic hypercoagulability and associated with abnormal coagulation and blood parameters [such as elevated D-dimer and C-reactive protein (CRP), lower hemoglobin (Hb)] as well as multiterritorial infarcts (8, –10)." (PMID 37021282, 2023). "Increased circHECTD1 expression has been linked to higher levels of C-reactive protein, proinflammatory cytokines, and National Institutes of Health Stroke Scale scores in the peripheral blood of AIS patients, suggesting that circHECTD1 may serve as a biomarker of inflammation in IS." (PMID 37759884, 2023). "There are several confounding factors while interpreting the CRP level, which might be affected by chronic diseases, cardiovascular risk factors, BMI, recent infection, surgery, fracture, stroke, and inflammation sensitive drugs (Turner, Kiernan, Leigh & Talbot, 2009)." (PMID 35201675, 2022). "Thus, patients with stroke with a thrombotic aetiology, underlying the atherosclerotic plaque process even before the stroke, may show higher concentrations of suPAR and CRP compared to patients with stroke with a cardiovascular aetiology." (PMID 35330458, 2022). "Therefore, in the early stage, high levels of CRP may be associated with clinical outcomes in patients with stroke." (PMID 36079002, 2022). "Therefore, high CRP levels and low serum albumin may be also associated with poor neurological outcomes in neurocritically ill patients with stroke." (PMID 36079002, 2022). "Also, plasma CRP detects early development of stroke-associated infections and may have a role in diagnostic criteria for SAP." (PMID 31037709, 2021).
Stroke (continued). "In multivariate analysis, galectin-3 remained a high stroke severity predictor with an adjusted OR of 1.16 (95% CI, 1.08–1.22; P<0.001), after adjusted for demographic characteristics, clinical findings at admission, vascular risk factors, stroke subtype, and serum levels of CRP and FSG." (PMID 33686023, 2021). "In the univariate analysis, serum CRP level above 9.17 mg/L was associated with higher depressive symptoms at day 8 (OR: 2.49, 95%CI: 1.45–4.29, P < 0.01) and CRP level above 6.7 mg/dL was associated with higher depressive symptoms 3 months after stroke (OR: 2.81, 95%CI: 0.99–3.31, P = 0.05)." (PMID 31996746, 2020). "Since CRP levels are associated with severity and size of the lesion, in minor stroke CRP levels are less likely to reflect stroke severity but might be a marker of underlying inflammation and therefore are less subject to variation depending on time from onset." (PMID 32733466, 2020). "In addition, association of CRP with post-stroke mortality may partly reflect inflammation-induced endothelial cell dysfunction and platelet activation." (PMID 30718369, 2019). "This study examined whether plasma high-sensitivity CRP (hsCRP) levels at onset were associated with clinical outcomes after acute ischemic stroke independent of conventional risk factors and acute infections after stroke." (PMID 27258004, 2016). "Furthermore, IL-6 and CRP are independent risk factors for stroke and myocardial infarction." (PMID 25574216, 2015). "The fact that the center of the rich-club, CRP, as well as other components are recognition molecules and acute-phase reactants indicates that the rich-club is activated first and then it stimulates a diverse network of other interacting partners leading to the overall stroke pathogenic network." (PMID 26310627, 2015). "In these individuals, who were randomised to placebo or treatment with pravastatin, IL-6, CRP, and fibrinogen all predicted cardiovascular death, and IL-6 in particular added significantly to conventional risk factors in predicting those suffering fatal myocardial infarction or fatal stroke." (PMID 19901972, 2009). "We therefore aimed to validate the suggestion that several markers of the acute phase response—CRP, IL-6, white cell count, fibrinogen, or glucose—are reliably associated with poor outcome after ischemic and hemorrhagic stroke in a large prospective cohort of stroke patients." (PMID 19901973, 2009). "Recent studies have shown a link between PM exposure and oxidative stress, which may impair endothelial-dependent vasodilation as well as increased levels of fibrinogen (an established risk factor for myocardial infarction and stroke), C reactive protein, IL-6, and IL-8." (PMID 17450221, 2007). "The interleukin (IL)-1β–IL-6–C-reactive protein (CRP) axis is central in stroke pathophysiology and turned out to be associated with recurrent strokes, not only restricted to atherothrombotic events [30▪,31]." (PMID 41311168, 2026). "Among biomarkers of systemic inflammation, C-reactive protein (CRP) has been widely used to assess stroke prognosis." (PMID 41300897, 2025). "Six variables were incorporated into the final model: history of stroke, serum sodium, hypersensitive C-reactive protein (hsCRP), C-reactive protein (CRP), basophil percentage, and mean corpuscular hemoglobin concentration (MCHC)." (PMID 40196863, 2025). "Only volume (p = 0.004) and CRP level (p = 0.031) showed statistically significant differences between cortical and subcortical strokes, suggesting a stronger inflammatory response and a tendency of higher oxidative component associated with cortical strokes." (PMID 41221512, 2025). "NIHSS: National Institutes of Health Stroke Scale; cfDNA: cell-free DNA; hsCRP: high-sensitivity C-reactive protein; mRS: modified Rankin Scale." (PMID 40406760, 2025).